WBP2NL (WBP2 N-terminal like)
Description:
May play a role in meiotic resumption and pronuclear formation, mediated by a WW domain-signaling pathway during fertilization.
Synonyms: PAWP; FLJ26145; MGC26816; GRAMD7
Tractability: No criterion of Open Targets' tractability assessment is met for any kind of drug.
Safety:
Unwanted effects reported when the protein is acted on. In parentheses: how it was acted on, where the effect was seen, and who reports it.
adverse events (source: ClinPGx)
Gene: Protein-coding gene on chromosome 22 (41,998,725 to 42,058,456, forward strand). Ensembl gene ENSG00000183066.
Subcellular location (Human Protein Atlas): Cytosol
Gene Ontology:
Molecular function: protein binding; chromatin DNA binding; transcription coactivator activity; WW domain binding
Biological process: regulation of cytosolic calcium ion concentration; egg activation; male pronucleus assembly; positive regulation of DNA-templated transcription
Cellular component: sperm flagellum; sperm head; nucleus; perinuclear theca
Genetic constraint (gnomAD): Loss-of-function variants: 27 observed, 25.27 expected, observed/expected ratio (o/e) 1.07, 90% interval 0.79 to 1.47. The upper end of that interval is the gene's LOEUF score, 1.47, which puts it in group 6 of 6, group 1 being the genes least tolerant of losing a copy. Missense variants: 370 observed, 408.46 expected, observed/expected ratio (o/e) 0.91, 90% interval 0.83 to 0.99. Synonymous variants: 151 observed, 153.34 expected, observed/expected ratio (o/e) 0.98, 90% interval 0.86 to 1.13.
Homologues: Orthologues: chimpanzee WBP2NL (96% identical), macaque WBP2NL (84% identical), mouse Wbp2nl (64% identical), rat Wbp2nl (64% identical), guinea pig WBP2NL (60% identical), dog WBP2NL (51% identical), tropical clawed frog wbp2nl (37% identical), Drosophila melanogaster Wbp2 (34% identical), zebrafish wbp2nl (30% identical), Caenorhabditis elegans C18B2.4 (25% identical), Caenorhabditis elegans wbp-2 (22% identical). Paralogues in human: WBP2 (34% identical).
Diseases named in the same sentence as WBP2NL in open-access papers:
WBP2NL is named in the same sentence as 5 diseases in open-access papers, as found by Europe PMC text mining. Sharing a sentence is not in itself a finding about the gene and the disease. The quoted sentences say what the papers report.
breast carcinoma (3 papers, 2017 to 2024). "WWP2 N-terminal-like (WBP2NL) is a testis-specific signaling protein that induces meiotic resumption and oocyte activation events and has been linked to breast cancer." (PMID 38554236, 2024). "Utilizing RT-PCR, including semi-nested RT-PCR, researcher has determined that the overexpression of WBP2NL observed in 90% of breast cancer tissues and in MDA-MB-231 cell line, respectively." (PMID 28724435, 2017). "Thus, both WBP2 and WBP2NL genes are highly related to the angiogenesis of breast carcinoma through the modulation of EGF, ER, and other downstream signaling proteins." (PMID 28724435, 2017). "Upregulation and downregulation of these genes in malignant breast cancer and normal breast cancer tissues leads us to speculate that WBP2NL potentially acts as an anti-apoptotic factor or coactivator in the development and progression of breast cancer." (PMID 28724435, 2017).
WBP2NL also shares sentences with these, for which no sentence is quoted: infertile (2 papers); cancer (1); Globozoospermia (1); vitiligo (1).